MTOR (mechanistic target of rapamycin kinase)
Diseases named in the same sentence as MTOR in open-access papers (continued):
Sharing a sentence is not in itself a finding about the gene and the disease.
rectal cancer (16 papers, 2013 to 2024). A primary or metastatic malignant neoplasm that affects the rectum. "High post-neoCRT p-mTOR was associated with distant metastasis in rectal cancer patients after neoCRT." (PMID 35201501, 2022). "Radioresistant PDOs displayed upregulation of the epithelial-mesenchymal transition (EMT) pathway and the PI3K/AKT/mTOR pathway, both of which have been associated with radioresistance in rectal cancer." (PMID 35860583, 2022). "The expression of PTEN was higher while the expression of p-4E-BP1 was lower in patients without local recurrence than in patients with local recurrence, suggesting that mTOR activation might be implicated in the local recurrence of rectal cancer." (PMID 38741069, 2024). "LncRNA DLGAP1-AS2 enhanced the radiotherapy resistance of rectal cancer cells by interacting with E2F1 to increase CD151 expression through activating the AKT/mTOR/cyclinD1 signaling pathway." (PMID 39119602, 2024). "The relationship among mTOR signaling pathway, PD-L1 and cytokines in rectal cancer should be elucidated in the future." (PMID 35201501, 2022). "We acknowledge the limited sample size in this study, however the effect of dual mTOR/AKT inhibition was consistent across all rectal cancer organoid models, suggesting that profiling more organoid models would have been redundant." (PMID 35860583, 2022). "We have shown that one of the mechanisms by which rectal cancer attains radioresistance is by upregulation of PI3K/AKT/mTOR." (PMID 35860583, 2022). "Subsequent studies encompassing larger and more homogeneous cohorts are warranted to further evaluate the effects of radiotherapy and pathway blocking drugs on PI3K/AKT/mTOR pathway downstream effectors and rarer subtypes of rectal cancer." (PMID 35860583, 2022). "Dual AKT/mTOR inhibitors should be prioritised for a neoadjuvant therapy trial to increase response rates in rectal cancer." (PMID 35860583, 2022). "Another mTOR inhibitor, rapamycin, was used in Phase I (13 patients) and II clinical trial (31 patients) with primary resectable rectal cancer, where patients received rapamycin one week before and during radiotherapy." (PMID 34638601, 2021). "Everolimus—an mTOR inhibitor was administered in 12 patients with primary resectable rectal cancer 14 days prior to the start of chemoradiotherapy and continued throughout the four-week course with 5-FU and radiotherapy." (PMID 34638601, 2021). "Rapamycin is an mTOR inhibitor which, when administered to rectal cancer patients 1 week before as well as during radiotherapy treatment, reduced the metabolic activity of tumours without affecting the tumour response to treatment." (PMID 34321074, 2021). "Two early Phase I/II clinical trials evaluated the role of mTOR inhibitors in conjunction with SCRT in rectal cancer patients." (PMID 32443649, 2020). "Further clinical trials are warranted to evaluate the role of mTOR inhibitors and dual pathway inhibitors in improving pCR rates in rectal cancer patients." (PMID 32443649, 2020). "Research focusing on the use of PI3K/AKT/mTOR pathway inhibitors to improve radiotherapy response in rectal cancer is still in its infancy." (PMID 32443649, 2020). "mTOR inhibitors were found to be safe in combination with chemotherapy and/or radiotherapy in cervical cancer, PC and rectal cancer." (PMID 32443649, 2020). "In this study, mTOR was also highly expressed in rectal cancer tissues, and 81 cases with high expression (81/148, 54.73%) were obtained, which was consistent with high GOLPH3 expression." (PMID 27634904, 2016). "In addition to VEGF, mammalian target of rapamycin (mTOR) inhibitors have also been investigated to combat angiogenesis in rectal cancer." (PMID 38623751, 2024). "Representative immunohistochemistry staining of mTOR, p-mTOR and programmed death ligand 1 (PD-L1) of the pre-neoCRT tissues and post-neoCRT biopsies in locally advanced rectal cancer." (PMID 35201501, 2022).
rectal cancer (continued). "However, additional studies are still needed to clarify the role of EGFR and the predictive potential of the MAPK/AKT and PI3K/AKT/mTOR pathways in rectal cancer." (PMID 34321074, 2021). "We identified six SMIs that radiosensitize K-RAS mutant rectal cancer cells: BEZ235 (PI3K/mTOR inhibitor), AZD7762 (Chk1/2 inhibitor), AZD8931 (pan-ErbB receptor inhibitor), AT-406 (inhibitor of apoptosis protein (IAP) family inhibitor), AZD6244 (MEK inhibitor), and Abt888 (PARP inhibitor)." (PMID 24349411, 2013). "However, it is conceivable that rare molecular subtypes of rectal cancer may exist that would be resistant to dual mTOR/AKT inhibition, and this could only be determined by screening on a very large bank of PDO." (PMID 35860583, 2022). "Mutations in both the MAPK/ERK pathway (e.g. BRAF, KRAS, NRAS, ERBB2, and ERBB3) and the PI3K/AKT/mTOR pathway (e.g. PIK3CA, IGF2, PTEN, and PIK3R1) are frequent in rectal cancer." (PMID 34321074, 2021). "Inhibition of PI3K and mTOR by BEZ235 appears to be a promising therapeutic approach, especially in combination with IR for rectal cancer." (PMID 24349411, 2013). "Whether the mTOR pathway is targeted by GOLPH3, with its inhibition reversing resistance to radiotherapy in rectal cancer needs to be addressed in future studies." (PMID 27634904, 2016).
spinal cord injury (16 papers, 2017 to 2026). Penetrating and non-penetrating injuries to the spinal cord resulting from traumatic external forces (e.g., WOUNDS, GUNSHOT; WHIPLASH INJURIES; etc.). "Our previous findings indicated that treatment with Netrin-1 could improve functional recovery through the stimulation of autophagy, by activating the AMP-activated protein kinase/mammalian target of rapamycin (AMPK/mTOR) signaling pathway in rats following spinal cord injury (SCI)." (PMID 29209172, 2017). "In conclusion, IL-1β may affect neuronal apoptosis and regeneration through the regulation of mTOR, FOXO, and GSK3 expression via the PTEN/AKT1 signaling pathway, thereby affecting neuronal survival and functional recovery after spinal cord contusion." (PMID 39262872, 2022). "In a spinal cord injury (SCI) model, overexpression of miR-17 was reported to facilitate glial scar formation and suppress the neurofilaments regeneration through targeting PTEN and stimulating the PI3K/Akt/mTOR pathway." (PMID 34187567, 2021).
Cirrhosis (15 papers, 2013 to 2025). A chronic disorder of the liver in which liver tissue becomes scarred and is partially replaced by regenerative nodules and fibrotic tissue resulting in loss of liver function. "Our study also showed a more frequent expression of intracellular MAPK and PI3K/AKT/mTOR proteins in tumors than in underlying cirrhosis, suggesting a critical role in HCC development." (PMID 33178273, 2020). "This could explain discrepancies in the observations of mTOR activation in obese children (with high mTOR) and adults; where low mTOR associates with lower Insulin receptor expression and increased cirrhosis due to lower HSC-killing activity." (PMID 33679803, 2021). "Also, in another tissue microarray study, we identified that mTOR was differently expressed in NAFLD cirrhosis compared with other causes of cirrhosis." (PMID 24738043, 2014). "Given that p-mTOR is upregulated in NASH-related cirrhosis and mTOR is regulated by ATAD3A in cow epithelial cells, we expected to see upregulation of ATAD3A during the progression of NAFLD." (PMID 35513069, 2022). "Finally, we investigated the expression of genes related to the TCA cycle and the upstream regulators of mTOR in circulating DCs and monocytes from patients with cirrhosis." (PMID 24322372, 2013). "Skeletal muscle of mice with cirrhosis induced by bile duct ligation (BDL) had myasthenia and a significant decrease in the expression levels of Akt and mTOR, while the expression of myostatin, which negatively regulated the activity of the Akt–mTOR axis, was increased." (PMID 37881635, 2023). "Kawaguchi pointed out that BCAAs, particularly leucine, could activate the mTOR signaling cascade and increase ALB synthesis in animal models of cirrhosis." (PMID 30210344, 2018). "Furthermore, the impaired mTOR signaling under ACM was consistent with the high expression of AMPK and the low expression of PDK1 in DCs and monocytes from patients with advanced cirrhosis." (PMID 24322372, 2013).
esophageal adenocarcinoma (15 papers, 2015 to 2024). A malignant tumor with glandular differentiation arising predominantly from Barrett mucosa in the lower third of the esophagus. "Atypical activation of GLI1 has been observed in esophageal adenocarcinoma (EAC) via the mTOR/S6K1 pathway which activates the transcription and oncogenic function of GLI1 phosphorylation by S6K1." (PMID 34944780, 2021). "However, studies on esophageal adenocarcinoma cells suggest that TNF-alpha activates GLI proteins through the mTOR pathway, specifically involving S6K1-mediated phosphorylation of GLI1 at Ser84." (PMID 39568072, 2024). "However, it is known that HER2 activates that pathway through the PI3K/AKT/mTOR signaling in human esophageal adenocarcinoma." (PMID 36294994, 2022). "We could recently show that GLI1 is activated via ERBB2 and PI3K/AKT/mTOR in esophageal adenocarcinoma in a SMO-independent manner." (PMID 28418873, 2017). "Importantly, tumor lysates from cranberry proanthocyanidin treated mice showed inactivation of PI3K/AKT/mTOR signaling as was observed in vitro utilizing a panel of esophageal adenocarcinoma cell lines." (PMID 27548236, 2016). "Finally, in esophageal adenocarcinoma JHEsoAD1 cells, pharmacologic inhibition of mTOR using cranberry proanthocyanidins or rapamycin induces autophagy resulting in cell death and survival, respectively." (PMID 27548236, 2016). "Cholestatic liver diseases result from a repeated exposure to unconjugated primary biliary acids, which may activate mTOR through the IκB kinase β (IKKβ)/Tuberous sclerosis 1 (TSC1)/mTOR pathway as demonstrated in some precancerous conditions such as Barrett’s esophagus." (PMID 32070029, 2020). "However, addition of exogenous SHH to the esophageal adenocarcinoma cell lines increased GLI activity and the combination of vismodegib and everolimus (mTOR antagonist) suppressed tumor growth more than either drug alone in vivo." (PMID 36010600, 2022). "TNF-α selectively stimulates GLI1 and promotes GLI1 nuclear localization via mTOR phosphorylation of S6K1 in human esophageal adenocarcinoma cell lines, independent of SMO." (PMID 36010600, 2022).
glomerulonephritis (15 papers, 2012 to 2025). A renal disorder characterized by damage in the glomeruli. "In our future research, we plan to conduct PCNA and mTOR knockdown experiments to further validate their roles in the protective effects of 1.25(OH)2D3 against glomerulonephritis." (PMID 39636964, 2024). "According to another study, autophagy is closely related to mTOR signal pathway inhibitors in the treatment of glomerulonephritis." (PMID 34221974, 2021). "The safety and efficacy of the mTOR inhibitor everolimus in halting the progression of glomerulonephritis require further investigation." (PMID 35008770, 2021). "Nevertheless, adverse effects of using mTOR inhibitors have been reported clinically in human renal allografts, glomerulonephritis and experimental renal disease." (PMID 35008770, 2021). "To study the mTOR activity in pauci-immune glomerulonephritis, we evaluated the expression of mTOR, PTEN and TGF-β1 in both glomerular and tubulointerstitial region of the kidney biopsy samples." (PMID 31658846, 2019). "To this end, we aimed to determine the role of mTOR pathway in the pathologic changes observed in kidney biopsies of patients with pauci-immune glomerulonephritis." (PMID 31658846, 2019). "Percentages of cells stained by mTOR in glomerular and tubulointerstitial areas of renal biopsy samples of patients with pauci-immune glomerulonephritis." (PMID 31658846, 2019). "The mTOR was expressed in substantial percentages of glomeruli of patients with pauci-immune glomerulonephritis." (PMID 31658846, 2019). "However, previously the role of mTOR pathway in pauci-immune glomerulonephritis pathogenesis was evaluated in only one study." (PMID 31658846, 2019). "The results of our study showed that mTOR pathway and it is regulators might contribute to the pathology seen in pauci-immune glomerulonephritis." (PMID 31658846, 2019). "In this study, we showed that mTOR was expressed in all tubulointerstitial areas of kidney biopsy samples with pauci-immune glomerulonephritis and the percentages of cells that is stained by mTOR is higher in tubulointerstitial area than glomerular region (p = .002)." (PMID 31658846, 2019). "Our study also revealed that mTOR expression in tubulointerstitial area might also be operative in the pathology of pauci-immune glomerulonephritis." (PMID 31658846, 2019). "Our study showed that glomerular or interstitial expression of PI3K/AKT/mTOR pathway may play a role in the pathogenesis of pauci-immune glomerulonephritis and mTORC1 inhibitors might provide a viable alternative for this disease." (PMID 31658846, 2019). "Thus, mTOR is essential for the proliferation of mesangial cells, as is the case of mesangioproliferative glomerulonephritis." (PMID 22685654, 2012). "However, it remains unclear whether 1.25(OH)2D3 can regulate the pathology and progression of glomerulonephritis through mTOR." (PMID 39636964, 2024). "Therefore, we aimed to evaluate the role of mammalian target of rapamycin (mTOR), which might be a potential therapeutic target, in kidney biopsies of patients with pauci-immune glomerulonephritis." (PMID 31658846, 2019). "Rab4A deletion in T cells and pharmacological mTOR blockade restrain CD98 expression, mitochondrial metabolism and lineage skewing and attenuate glomerulonephritis." (PMID 38519468, 2024). "This study also revealed that mTOR expression in tubulointerstitial area might be related with glomerular mTOR expression and PTEN staining and fibrosis observed in tubulointerstitial area of pauci-immune glomerulonephritis." (PMID 31658846, 2019).
liposarcoma (15 papers, 2014 to 2025). A usually painless malignant tumor that arises from adipose tissue. "Taken together, these findings suggest that activation of the AKT/mTOR pathway in liposarcoma can occur either through activating PIK3CA gene mutations or by alternative cancer mechanisms." (PMID 24695632, 2014). "The effect of si-KIF20A antagonized the activating influence of DEPDC1 overexpression on AKT/PI3K/mTOR in liposarcoma cells." (PMID 40600015, 2025). "Western blotting verified that Apatinib downregulated the TYMS/STAT3/PD-L1 pathway and inhibited liposarcoma proliferation by suppressing the RRM2/PI3K/AKT/mTOR pathway." (PMID 34868934, 2021). "In this study, we report for the first time that AZD1208 inhibits the growth of 93T449 human liposarcoma cells through Pim-3, 4EBP-1, mTOR, S6, eIF-2α, STAT-3 and AMPK." (PMID 30654529, 2019). "In summary, this is the first study reporting that AZD1208 has a cytostatic effect in human liposarcoma cells, which is be mediated through control of the expression and/or phosphorylation of Pim kinases, 4EBP-1, mTOR, S6, eIF-2α, STAT-3 and AMPK." (PMID 30654529, 2019). "Another new approach of our study is to inhibit PIK3 signaling with a dual inhibitor of PI3K/mTOR in liposarcoma." (PMID 24695632, 2014). "However, we did not perform the pharmacological inhibition of PI3K or Akt experiments to validate that DEPDC1 induces the proliferation and motility of liposarcoma cells through the PI3K/Akt/mTOR signaling pathway." (PMID 40600015, 2025). "Furthermore, the activation of the PI3K/AKT/mTOR signaling pathway in liposarcoma significantly enhances the rate of cell proliferation and cellular vitality." (PMID 40600015, 2025). "In conclusion, this study suggested that DEPDC1 might interact with KIF20A to promote the occurrence and progression of liposarcoma by activating PI3K/AKT/mTOR signaling pathway." (PMID 40600015, 2025). "Furthermore, the PI3K/AKT/mTOR signaling pathway plays a pivotal role in various cellular processes that contribute to the malignant phenotype of liposarcoma." (PMID 40600015, 2025). "Furthermore, inhibition of the pathway and its downstream effector, mTOR, has also been found to induce apoptosis in liposarcoma cell lines." (PMID 35887151, 2022). "Apatinib may inhibit liposarcoma cell proliferation through RRM2/PI3K/AKT/mTOR signaling pathway, and down-regulate PD-L1 through TYMS/STAT3 signaling pathway." (PMID 34868934, 2021). "Apatinib might inhibit liposarcoma cell proliferation through the RRM2/PI3K/AKT/mTOR signaling pathway and downregulate PD-L1 via the TYMS/STAT3 signaling pathway." (PMID 34868934, 2021). "We hypothesized that inhibition of AKT/mTOR pathway in liposarcoma would lower the apoptotic threshold and increase chemotherapy sensitivity." (PMID 24695632, 2014). "The published studies demonstrated elevated activation of the PI3K/AKT/mTOR and MAPK pathways in liposarcoma, as compared to benign adipose tissue." (PMID 40600015, 2025). "The deletion of KIF20A partially mitigated the promoting effect of DEPDC1 on the malignant phenotype of liposarcoma cells and the activation of PI3K/AKT/mTOR signaling pathway." (PMID 40600015, 2025). "We proposed that in liposarcoma, the expression of DEPDC1 was positively correlated with the activation of the PI3K/AKT/mTOR pathway." (PMID 40600015, 2025). "In line with published studies, our analysis revealed high activation of PI3K/AKT/mTOR and MAPK pathways in liposarcoma compared to benign adipose tissue." (PMID 35887151, 2022). "In summary, this is the first report demonstrating that AZD1208 inhibits growth of liposarcoma cells and that this activity is mediated through Pim-3 kinase, STAT-3, mTOR, S6 and AMPK expression and phosphorylation pathways." (PMID 30654529, 2019). "PI-103, a dual PI3K/mTOR inhibitor, effectively inhibited the activation of the PI3K/AKT in liposarcoma cell lines and induced apoptosis." (PMID 24695632, 2014).
liposarcoma (continued). "Furthermore, this study uncovered a novel regulatory mechanism of DEPDC1 in liposarcoma, wherein it enhanced PI3K/AKT/mTOR signaling to exacerbate malignant phenotypes." (PMID 40600015, 2025). "To determine whether Apatinib modulates liposarcoma cell proliferation through the RRM2/PI3K/AKT pathway, we used WB to measure the protein levels of RRM2, PI3K, p-PI3K, AKT, p-AKT, mTOR, and p-mTOR." (PMID 34868934, 2021). "Moreover, the overexpression of DEPDC1, coupled with the simultaneous knockdown of KIF20A in liposarcoma cells, partially inhibited the progression in malignant phenotypes of these cells and the activation of PI3K/AKT/mTOR signaling pathway compared to the control groups." (PMID 40600015, 2025). "Interestingly, in our current study, AKT and mTOR activation were also seen in PIK3CA non-mutant liposarcoma samples." (PMID 24695632, 2014).